SDC1 (syndecan 1)
Diseases named in the same sentence as SDC1 in open-access papers (continued):
Sharing a sentence is not in itself a finding about the gene and the disease.
liver diseases (7 papers, 2019 to 2024). "Contrary to HF, syndecan-1 has a protective effect in liver disease, its overexpression being associated with the inhibition of hepatic fibrosis." (PMID 37109427, 2023). "According to our previous studies the amount of heparan-sulphate and chondroitin-sulphate increases in various primary liver diseases, associated with altered expression of syndecan-1." (PMID 30826971, 2020). "This study was limited by the small number of cases, and a larger study with a more extensive disease range should be done to study the expression of syndecan-1 in liver diseases." (PMID 38022112, 2023). "Another important characteristic of syndecan-1 is reflected by its major role in the liver diseases, as its serum concentrations tend to increase in those pathologies associated with liver fibrosis." (PMID 37109427, 2023). "Of course, despite its overall beneficial effects, the presence of persistently increased levels of syndecan-1 generally reflects the activity of the liver aggression or a more rapid progression of a chronic, previously stable liver disease." (PMID 37109427, 2023). "Our aim was to correlate the amount of syndecan-1 in primary liver diseases and colorectal adenocarcinoma metastasis with relevant clinical data." (PMID 30826971, 2020). "In our study, we aimed to assess the expression of syndecan-1 (CD138) in various liver diseases." (PMID 38022112, 2023). "Due to liver diseases the amount of syndecan-1 increases in the liver." (PMID 30826971, 2020). "Liver diseases are often accompanied by quantitative changes of syndecan-1." (PMID 32977498, 2020). "Syndecan-1 is not a reliable marker for differentiating the etiology of liver disease." (PMID 38022112, 2023).
nephritis (7 papers, 2014 to 2023). Inflammation of renal tissue. "Syndecan-1 deficiency also causes high immunoglobulin production in an Ab-dependent nephritis model." (PMID 28045014, 2017). "In contrast, data also indicate that HSPGs may be anti-inflammatory, for example in disease models of nephritis and lung inflammation using sdc-1 and sdc-4 knockout mice." (PMID 25015005, 2014).
pancreatic adenocarcinoma (7 papers, 2015 to 2025). "DNA topoisomerase II alpha, syndecan 1, maternal embryonic leucine zipper kinase and proto-oncogene receptor tyrosine kinase Met were significantly linked with poor survival in pancreatic adenocarcinoma." (PMID 31412643, 2019). "The diagnostic capabilities and specificity to pancreatic adenocarcinoma of Syndecan-1 targeted liposomes were evaluated both in vitro and in vivo." (PMID 26627455, 2015). "It was identified that the expressions of CXCR4, HIF1A, ZEB1, and SDC1 in pancreatic adenocarcinoma (PAAD) were controlled by circ-UBAP2 and miR-494." (PMID 32665846, 2020). "Our goal was to develop a Syndecan-1 tagged liposome containing fluorescent dye as an improved contrast agent for detection of pancreatic adenocarcinoma in vivo using multispectral optoacoustic tomography." (PMID 26627455, 2015). "Syndecan-1 tagged liposomes actively target pancreatic adenocarcinoma with minimal off-target binding in vivo." (PMID 26627455, 2015). "Syndecan-1 (Sdc1) has been shown to bind specifically to pancreatic adenocarcinoma, making it a promising targeting ligand for a theranostic nanoparticle." (PMID 26627455, 2015). "A previous study indicated that Syndecan 1 (SDC1) might be a novel immune-related prognostic biomarker for pancreatic adenocarcinoma." (PMID 36983711, 2023). "circUBAP2 modulates pancreatic adenocarcinoma tumorigenesis by regulating the levels of hsa-miR-494 and the expression of CXCR4, HIF1A, ZEB1, SDC1, and TWIST132." (PMID 33707417, 2021). "This study examines the feasibility of using Syndecan-1 tagged liposomes as a theranostic nanoparticle for pancreatic adenocarcinoma, using MSOT to evaluate the specificity of these targeted liposomes for pancreatic adenocarcinoma in vivo." (PMID 26627455, 2015).
respiratory failure (7 papers, 2019 to 2024). The significant impairment of gas exchange within the lungs resulting in hypoxia, hypercarbia, or both, to the extent that organ tissue perfusion is severely compromised. "Syndecan-1 and sTM—alone and in conjunction—have been associated with the risk of developing acute respiratory failure as well as outcomes of manifest respiratory failure." (PMID 35094711, 2022). "Further, in these septic subjects, elevations of syndecan-1 are associated with heightened risks of developing respiratory failure and increased mortality." (PMID 36297099, 2022). "It is important to consider that in clinical studies circulating levels of syndecan-1 showed the strongest associations with neutrophil activation biomarkers and adverse clinical outcomes in patients with respiratory failure." (PMID 34576076, 2021). "To summarize, the Syndecan-1 has previously been tested as a marker for the development of acute respiratory failure, and the question of whether an association exists is equivocal." (PMID 35094711, 2022). "We tested the association of endotheliopathy—indicated by Syndecan-1, sTM, and PECAM-1 levels in plasma—with patient outcomes and disease severity in acute respiratory failure." (PMID 35094711, 2022). "To find out, we assessed the association of endotheliopathy, as reflected by plasma levels of Syndecan-1, sTM, and PECAM-1, with clinical outcomes and disease severity in acute respiratory failure requiring MV in the ICU." (PMID 35094711, 2022). "However, their results suggest syndecan-1 as a strong predictor of respiratory failure instead of endocan, which is not in line with our results." (PMID 31065299, 2019).
rheumatoid arthritis (7 papers, 2019 to 2026). A chronic, systemic autoimmune disorder characterized by inflammation in the synovial membranes and articular surfaces. "In addition to the increase in inflammatory cytokines, patients with SLE, but not patients with rheumatoid arthritis, manifest with elevated serum levels of CD138 (syndecan-1)." (PMID 34364875, 2021).
aneurysm (6 papers, 2021 to 2025). Bulging or ballooning in an area of an artery secondary to arterial wall weakening. "The data that emerged indicated a greater expression of syndecan-1 in the media of patients affected by aneurysms, especially within the smooth muscle cells." (PMID 39940978, 2025). "After 3 days of Ang II infusion, the proportions of the developed aneurysms were as follows for SDC-1+/+ and SDC-1−/− mice respectively: TAA (40 vs. 35%), AAA (20 vs. 6%), and both TAA and AAA (0 vs. 6%)." (PMID 35548440, 2022). "Recent research using animal models of aneurysm development indicate an important role for Sdc-1 in preventing and counteracting aneurysm pathogenesis." (PMID 34203009, 2021). "Considering that the local expression of Sdc-1 is indicated to protect from aneurysm formation, the increased aortic expression of Sdc-1 detected in T2D patients may contribute to a reduced prevalence of ascending AAs in T2D." (PMID 34203009, 2021). "It encompasses four components: syndecan-1, syndecan-2, and syndecan-4 (with syndecan-3 only expressed in neural tissue), which have a fundamental role in regulating the events of acute and chronic aorta damage subsequently correlated with the formation of aneurysms." (PMID 39940978, 2025). "When analyzing aneurysm incidence after 28 days of Ang II infusion, 73% of SDC-1+/+ mice developed TAA vs. 52% in SDC-1−/− mice." (PMID 35548440, 2022). "The survival rate of SDC-1+/+ and SDC-1−/− mice was similar during the course of Ang II infusion, indicating that SDC-1 deficiency did not alter the viability of the mice that developed aneurysm." (PMID 35548440, 2022). "However, it is not known whether aortic Sdc-1 expression is increased in patients with T2D and the potential role for elevated fasting plasma GLP-1 (fpGLP-1) nor is it known whether a macrophage-specific expression of Sdc-1 is part of a response to aneurysm formation in patients." (PMID 34203009, 2021).
chronic lymphocytic leukemia (6 papers, 2015 to 2023). "Studies assessing the correlation between soluble SDC1 in plasma and clinical outcome in patients with chronic lymphocytic leukemia have shown that soluble SDC1 levels were significantly higher in these patients compared to healthy control subjects." (PMID 26293675, 2015).
inflammatory breast carcinoma (6 papers, 2019 to 2023). An advanced, invasive breast adenocarcinoma characterized by the presence of distinct changes in the overlying skin. "This is following our previous observation of a co-regulation of CD44 and Sdc-1 in clinical samples of inflammatory breast cancer." (PMID 34070901, 2021). "For instance, signaling via the IL-6/STAT-3, Notch and EGFR signaling axis through the cell surface receptor syndecan-1 (CD138) has been established as a novel regulatory pathway responsible for the CSC phenotype in inflammatory breast cancer." (PMID 33809315, 2021). "Remarkably, syndecan-1 seems to be overexpressed in inflammatory breast cancer, making it a potential biomarker." (PMID 32351878, 2020). "Moreover, in inflammatory breast cancer cells, the downregulation of Sdc-1 decreased the protein levels of IL-6, IL-8, and growth-regulated protein GRO-alpha (CXCL1), and GRO a/b/g." (PMID 34070901, 2021). "Syndecan-1 was reported to play an immunomodulatory function in the polarization of CD4+ T helper (Th) cells that were isolated from the TME of inflammatory breast cancer (IBC) and non-IBC patients." (PMID 32351878, 2020). "For example, Sdc-1 expression in inflammatory breast cancer is correlated with CD44, Notch-1, and Notch-3 expression, and siRNA knockdown of Sdc-1 results in a weaker CSC phenotype and reduced expression of Notch-1-4 and Hey1 in inflammatory breast cancer cells." (PMID 33102470, 2020). "Herein, we aimed to identify the immunomodulatory role of tumor Syndecan-1 (CD138) in the polarization of CD4+ T helper (Th) subsets isolated from the tumor microenvironment of inflammatory breast cancer (IBC) and non-IBC patients." (PMID 31145753, 2019).
injury (6 papers, 2014 to 2023). Damage inflicted on the body as the direct or indirect result of an external force, with or without disruption of structural continuity. "MMP-7 and MMP-9 are known to cleave HS proteoglycans (including syndecan-1) and have been implicated in epithelial glycocalyx degradation in LPS- and bleomycin-induced lung injury." (PMID 34874923, 2022). "We found increased levels of syndecan-1 indicating shedding of the glycocalyx which has been associated with poor outcome in trauma patients, whereas RHI increased as a measure of improved endothelial functionality." (PMID 25505423, 2014). "Endothelial damage identified by elevated plasma syndecan-1 and soluble vascular cell adhesion molecule-1 (sVCAM-1) was present in all trauma-induced shock groups." (PMID 33685634, 2021). "Syndecan-1 is among the best-established markers of glycocalyx shedding, the plasma concentrations of the latter, as well as of heparan sulfate, chondroitin sulfate and soluble thrombomodulin are considerably elevated in trauma patients." (PMID 33740916, 2021). "Additionally, syndecan-1 can be used as a surrogate biomarker for non-cardiac organ dysfunction, as its highs levels can accurately reflect early acute kidney and liver injury." (PMID 37109427, 2023).
invasive ductal breast carcinoma (6 papers, 2008 to 2018). The most common type of invasive breast carcinoma, accounting for approximately 70% of breast carcinomas. "Our data are in agreement with other studies showing that both loss of syndecan-1 epithelial expression and syndecan-1 stromal expression are associated with poor clinical outcome in many cancers and in addition show that this is also true in cases of invasive ductal breast carcinomas." (PMID 18542065, 2008). "A tissue microarray of invasive ductal breast carcinoma specimens indicated high expression of SDC1 in the breast epithelium of more than half of the patients, whereas stromal expression was observed in only one third of the patients." (PMID 26293675, 2015). "Evaluation of SDC1 expression in invasive ductal carcinoma indicated that cytoplasmic expression of SDC1 was positively correlated with WNT1 (a proto-oncogene) and membranous expression of SDC1 was positively correlated with p16 (a tumor-suppressor protein)." (PMID 26293675, 2015). "High SDC1 expression was reported in triple-negative invasive ductal breast carcinomas compared to normal breast tissue." (PMID 26293675, 2015). "To better understand the mechanisms of the SDC1 expression in invasive ductal carcinoma, we studied the correlations between SDC1 expression and related gene expressions (RSPO1, WNT1, WT1, and P16)." (PMID 24373193, 2013). "The tumours from 80 patients diagnosed with invasive ductal breast carcinomas were used to construct a tissue microarray, which was stained with syndecan-1 by immunohistochemistry." (PMID 18542065, 2008). "This study determined and compared Sdc1 expression in the tumor cells and stroma of 30 invasive lobular and 30 invasive ductal breast carcinomas (ILCs/IDCs), also in the axillary node metastases of ductal type, and correlated it with clinical and tumor parameters." (PMID 30151336, 2018). "Using 100 cases of invasive ductal carcinoma tissue, we screened expressions of RSPO1, WNT1, WT1, P16, and SDC1 using immunohistochemistry." (PMID 24373193, 2013). "Our study shows that 61.25% of our patients with invasive ductal breast carcinomas overexpressed syndecan-1 within their carcinoma cells, whereas lacking it in the stroma (E+S−) and that 30% lacked syndecan-1 within the tumour cells but expressed it in their stroma (E−S+)." (PMID 18542065, 2008).
leukemia (6 papers, 2015 to 2021). A malignant (clonal) hematologic disorder, involving hematopoietic stem cells and characterized by the presence of primitive or atypical myeloid or lymphoid cells in the bone marrow and the blood. "Sdc1 knockdown was confirmed by PCR, as well as by flow cytometry in leukemia cells to ensure that GFP+ cells tracked were deficient for Sdc1 expression." (PMID 33243988, 2020). "To test whether Sdc1 may be important for propagation of established bcCML we assessed the capacity of control and Sdc1-deficient leukemia cells to propagate disease in vitro and in vivo." (PMID 33243988, 2020). "Interestingly, there was a striking difference in leukemia distribution in the bone marrow and spleen, with loss of Sdc1 leading to a much steeper decline in the spleen (~5-fold reduction compared to control) compared to the bone marrow (~1.3-fold, femur, 2-fold, calvarium)." (PMID 33243988, 2020). "Further, transplantation of BCR-ABL/NUP98-HOXA9-infected Sdc1−/− KLS cells resulted in a markedly lower (sevenfold) leukemia burden in vivo 14 days post-transplant." (PMID 33243988, 2020). "Control leukemia cells traveled at 1.0 ± 0.2 μm/s on average, whereas Sdc1 knockdown leukemia cells traveled at 0.37 ± 0.05 μm/s." (PMID 33243988, 2020). "The screen we performed to identify differentially expressed surface proteins on Msi2+ leukemia cells led to the identification of Sdc1 as a key regulator of bcCML growth and propagation." (PMID 33243988, 2020). "Our discovery that Sdc1 plays a role in bcCML indicates that it may in fact be a core regulatory mechanism for leukemias as well, and suggests that interactions with their niche are a critical source of support for leukemia cells." (PMID 33243988, 2020).
liver fibrosis (6 papers, 2019 to 2025). "Results presented in literature underline the beneficial effect of syndecan-1 in the early stages of liver fibrosis, by way of binding and enhancing the clearance of TGFβ1, an important promoter of fibrogenesis." (PMID 31815014, 2019). "This can be explained by the fact that, by attaching to TGF-β1, syndecan-1 accelerates the clearance of this important promotor of hepatic fibrosis." (PMID 37109427, 2023). "We previously highlighted the use of syndecan-1 as a reliable marker of liver fibrosis, given the involvement of its extra membrane domain in the synthesis of MMPs, particularly MMP-14." (PMID 37109427, 2023). "This is somewhat conflictual with the correlation found between high serum levels of shed syndecan-1 and the prediction of liver fibrosis in chronic hepatitis C patients." (PMID 34065048, 2021). "In the meantime this over production of syndecan-1 goes together with its increased shedding, which seemed to be beneficiary in experimental liver fibrosis." (PMID 30826971, 2020). "The chains of syndecan-1 are binding several molecules, facilitating intercellular signalling, the most important interactions in liver fibrosis being the ones with TGFβ1, basic fibroblast growth factor (bFGF), and hepatocyte growth factor (HGF)." (PMID 31815014, 2019). "Even though biomarkers for noninvasive assessment of liver fibrosis have been widely tested, there are scarce data about the utility of syndecan-1 in the evaluation of cirrhotic patients." (PMID 31815014, 2019). "Taken into account that these two clinical entities can progress to liver fibrosis or even cirrhosis, the dynamic evaluation of syndecan-1 serum levels in patients with these chronic disorders seems reasonable." (PMID 31815014, 2019). "From a clinical perspective, elevated SDC1 could relate to inflammation, cardiac and/or hepatic fibrosis, and endothelial damage." (PMID 38791454, 2024). "Syndecan-1—a transmembrane proteoglycan that exerts its functions mainly via its heparane sulfate chains—is a very promising biomarker, correlated not only with the degree of cardiac fibrosis but also with the severity of liver fibrosis." (PMID 31815014, 2019). "However, in the case of patients with chronic liver diseases and concomitant clostridium colitis, with a significant inflammatory status, the use of syndecan-1 as a reliable liver fibrosis biomarker is marked by controversy because of its important variations in inflammatory diseases." (PMID 31815014, 2019). "Hence, a routine assessment of syndecan-1 levels in these HCV-infected patients could unmask a subclinical progression towards liver fibrosis or, more often, an early cardiac dysfunction." (PMID 31815014, 2019). "Elevated serum levels of shed syndecan-1 have been proposed as biomarkers of prediction of liver fibrosis but not of liver inflammation in chronic hepatitis C patients." (PMID 34065048, 2021). "Syndecan-1 may also be used as a reliable biomarker for the noninvasive assessment of liver fibrosis." (PMID 31815014, 2019).
metastatic carcinoma (6 papers, 2014 to 2025). A carcinoma which has spread from the original site of growth to another anatomic site. "The Ki67 proliferation index in metastatic carcinoma cells was significantly (p = 0.0002) decreased by 86% in Sdc1−/− mice compared to their Sdc1+/+ counterparts." (PMID 29976229, 2018). "According to our results, a high Sdc1 expression in the tumor epithelium of the metastasis, almost equal to that of a primary tumor, suggests direct involvement of the Sdc1 in progression, not only of primary ductal carcinomas but also of metastatic carcinomas." (PMID 30151336, 2018).